PIK3CA (phosphatidylinositol-4,5-bisphosphate 3-kinase catalytic subunit alpha)
Diseases named in the same sentence as PIK3CA in open-access papers (continued):
Sharing a sentence is not in itself a finding about the gene and the disease.
mucinous tumors (5 papers, 2012 to 2024). "The univariate model suggested that patients with PIK3CA mutations more frequently had mucinous tumors (p = 0.04)." (PMID 22675430, 2012). "In univariate analysis, patients with PIK3CA mutations more frequently had mucinous tumors (p = 0.04), and tended to less frequently have liver metastases compared to patients with PIK3CA wild-type tumors." (PMID 22675430, 2012). "In the multivariate analysis, mucinous tumors were marginally significant (p-value = 0.05), with patients having mucinous tumors more frequently having PIK3CA mutations (OR 2.61; 95% CI 0.99–6.87)." (PMID 22675430, 2012). "In the multivariate regression model for clinical characteristics KRAS mutations were associated with an increased incidence of lung and bone metastases and decreased incidence of adrenal metastases; PIK3CA mutations were marginally correlated with mucinous tumors (p = 0.05)." (PMID 22675430, 2012). "These include: FH, GMPS, PIK3CA, EIF4A2, ZNF384, and SS18L1 (amplifications in serous tumors); TET2, FGFR10P, NF1, ERBB2, and SH3GL1 (deletions in serous tumors) and ERBB2 (amplifications in mucinous tumors)." (PMID 23078675, 2012).
myxoid liposarcoma (5 papers, 2014 to 2025). A liposarcoma characterized by the presence of round non-lipogenic primitive mesenchymal cells and small signet ring lipoblasts within a myxoid stoma with a branching vascular pattern. "All four PIK3CA mutations were identified in myxoid liposarcoma out of 10 total samples with this histological subtype (33%)." (PMID 24695632, 2014). "One patient with high grade myxoid liposarcoma had a pathogenic PIK3CA mutation identified." (PMID 40144205, 2025). "Similarly, a proportion of myxoid liposarcoma harbor PIK3CA alterations." (PMID 37998367, 2023).
oropharyngeal carcinoma (5 papers, 2013 to 2023). Carcinoma, predominantly squamous cell, arising from the epithelial cells of the oropharynx. "Hotspot mutation in PIK3CA is frequently observed in HPV-induced oropharyngeal carcinoma; however, we observed missense variants in only two samples." (PMID 34136393, 2021). "Mutations in PIK3CA gene were associated with improved outcomes among metastatic HPV-positive oropharyngeal cancer, with similar results reported in HPV-negative oropharyngeal cancer." (PMID 31905960, 2019). "Note that PIK3CA mutations only occur in a small subset of HPV(−) oropharyngeal cancer (9% cases) as compared to HPV(+) HNSCC (36% cases)." (PMID 29933636, 2018). "PIK3CA mutations were identified by Sanger sequencing in 23 of 75 (31%) HPV-positive oropharyngeal carcinomas, including exon 9 (p.E545K [n = 10] and p.E542K [n = 5]) or exon 20 (p.H1047Y, n = 2) mutations." (PMID 24341335, 2013). "The lack of specific clinicodemographic features concerned with PIK3CA mutation has been suggested in oropharyngeal cancers, although some studies have characterized rare patients with decreased exposure to tobacco or HPV-positivity by the clinicopathological features of PIK3CA mutation." (PMID 36979829, 2023).
pituitary tumor (5 papers, 2012 to 2023). A benign or malignant neoplasm affecting the pituitary gland. "Consistent with the role of PI3K activation in PitNETs, the mutations of the PIK3CA gene that encodes the p110 catalytic subunit of PI3K were assessed in 353 pituitary tumors." (PMID 37109772, 2023). "The somatic mutations of the PIK3CA gene were detected in about 9% of invasive pituitary tumors but were note detected in any of the non-invasive tumors, and the mutation was associated with an increased disease recurrence." (PMID 37109772, 2023). "PIK3CA amplifications or mutations occur in around a third of pituitary tumors, and PIK3CA mutations are associated with invasive disease." (PMID 26793165, 2015).
prostate tumors (5 papers, 2010 to 2026). "Alterations in insulin pathway genes, such as PTEN, FOXO, and PIK3CA, are mutated in up to 32%, 15%, and 11% of localized prostate tumors, respectively." (PMID 42192996, 2026). "A mutational profiling of AKT1 and of the mutational hotspots in PIK3CA and PIK3R1 was carried out in samples from primary and recurrent prostate tumours." (PMID 20407443, 2010). "This is due to a study of Pten loss-induced prostate tumor formation in mice, showing that the genetic deletion of Pik3cb encoding p110β isoform, but not deletion of Pik3ca, inhibits tumorigenesis together with reduction of Akt phosphorylation." (PMID 34681745, 2021).
PTEN hamartoma tumor syndrome (5 papers, 2020 to 2025). An autosomal dominant syndrome caused by pathogenic variants in the PTEN gene, characterized by hamartomas, overgrowth, neurodevelopmental disorders and an increased risk of various cancers, including breast, thyroid, and endometrial cancer. "PTEN hamartoma tumor syndrome (PHTS) is a rare autosomal dominant syndrome with an estimated prevalence of ~ 1:200,000, caused by germline inactivating mutations or deletions in the PTEN tumor suppressor gene (10q23.31) or in other functionally related genes (e.g., PIK3CA, AKT1)." (PMID 40111709, 2025). "Segmental overgrowth, or lateralized overgrowth, includes the phosphoinositide-3-kinase, catalytic, alpha polypeptide (PIK3CA) − related overgrowth spectrum (PROS), mosaic RASopathies, PTEN hamartoma tumor syndrome and Beckwith–Wiedemann spectrum." (PMID 36175890, 2022).
salivary gland tumors (5 papers, 2015 to 2025). "PIK3CA mutations were found in 59% of HRAS-mutant salivary gland tumors but due to the limited number of KRAS- and NRAS-mutant tumors of this lineage this was not significantly different, but was more prevalent than in other HRAS-mutant cancers (p<0.05)." (PMID 37503077, 2023). "The PIK3CA variant occurred at amino acid E542K in two rare salivary gland tumors, myoepithelioma and mucoepidermoid tumor." (PMID 32570879, 2020). "Importantly, aberrations in the PI3K pathway (PIK3CA, PIK3R1, PTEN or AKT) were commonly seen in salivary gland tumors (28/117 [23.9%])." (PMID 26247885, 2015).
small cell carcinoma (5 papers, 2015 to 2022). A neuroendocrine carcinoma composed of small malignant cells which are often said to resemble "oat cells" under the microscope. "These include additional mutations in EGFR (40–60%) and mutations in PIK3CA (5%) and BRAF (1%), amplification of MET (5–10%) and ERBB2 (12%), phenotypic transformation such as to small cell carcinoma (3–14%) and the epithelial to mesenchymal transition." (PMID 27304188, 2016).
steatosis (5 papers, 2019 to 2025). Increased lipid within the cytoplasm of cells. "She had a recurrent somatic mutation in PIK3CA (NM_006218.3: c.1357G>A, p.Glu453Lys), elevated HbA1c levels, and pancreatic steatosis." (PMID 31263565, 2019). "On the other hand, phosphatidylinositol-4,5-bisphosphate 3-kinase catalytic subunit alpha (Pik3ca) overexpression in mouse hepatocytes generates steatosis and HCC, while deletion of Akt2 from mouse hepatocytes leads to the accumulation of triglycerides (TG) in the liver." (PMID 40282551, 2025). "RUNX1 target genes, CCL2 and PIK3CA significantly correlated to NAS, steatosis, inflammation grade and fibrosis score, NOS3 to NAS and inflammation grade and PRKCE to NAS and steatosis grade." (PMID 31635436, 2019). "Moreover, after the treatment with the association, the increment in the expression of the genes related to cell survival, AKT1, MAPK8, PIK3CA (four times), and FAS (eight times), and to anti-inflammatory signaling, IL10 (four times), was observed in respect to the steatosis control." (PMID 36770927, 2023).
anal squamous cell carcinoma (4 papers, 2014 to 2024). A squamous cell carcinoma (SCC) arising from the anal canal or the anal margin (perianal skin).
brain malformation (4 papers, 2015 to 2024). "Gene-specific recommendations were recently reported for PIK3R1, and for AKT3, MTOR, PIK3CA and PIK3R2 by the ClinGen Brain Malformation Variant Curation Expert Panel." (PMID 38778413, 2024). "Variants in PI 3-kinases and their regulatory subunits, PIK3CA, PIK3R2 as well as one of their downstream targets, AKT3, have all been implicated in PMG and associated brain malformation phenotypes." (PMID 25855803, 2015).
colorectal adenoma (4 papers, 2011 to 2022). An adenoma that arises from the colon or rectum. "In colorectal adenomas, however, PIK3CA mutations are less common, with mutation frequencies around 3%, indicating that mutations in PIK3CA generally would arise late in tumorigenesis." (PMID 22848674, 2012).
ductal carcinoma in situ (4 papers, 2014 to 2025). "Even though the mutation frequency of PIK3CA was similar between invasive and ductal carcinoma in situ BC, PIK3CA gene mutation was reported to be driver mutation in both BC subtypes." (PMID 35251373, 2022).
endocervical adenocarcinoma (4 papers, 2021 to 2025). An adenocarcinoma that arises from the endocervix. "Prevalent molecular alterations in usual-type HPV-associated endocervical adenocarcinomas include mutations in PIK3CA, KRAS, and PTEN, and abnormalities in segments of the PI3K/Akt/mTOR signaling cascade, some of which have predictive and prognostic value 34–37." (PMID 33570865, 2021).
Ewing sarcoma (4 papers, 2014 to 2025). A small round cell tumor that lacks morphologic, immunohistochemical, and electron microscopic evidence of neuroectodermal differentiation. "Mutations in PI3K family genes, especially PIK3CA or PIK3R1 are often present in glioblastoma multiforme, testicular germ cell tumors, and Ewing’s sarcoma, resulting in alteration pattern of PAM pathway." (PMID 37596643, 2023).
Fibroadenoma (4 papers, 2020 to 2025). A benign tumor of the breast characterized by the presence of stromal and epithelial elements.
glioneuronal tumors (4 papers, 2020 to 2025). "Another mdPCR assay targeting PIK3CA mutations, which also constitute a common genetic alteration of pediatrics glial and glioneuronal tumors, has also been designed." (PMID 33282733, 2020). "The histopathological report of the specimen tissue stated a rosette-forming glioneuronal tumor, WHO grade I with a mutation in the fibroblast growth factor receptor 1 (FGFR1) and in the phosphatidylinositol-4,5-bisphosphate 3-kinase catalytic subunit alpha (PIK3CA)." (PMID 39860615, 2025).
human papilloma virus infection (4 papers, 2015 to 2024). An infectious process caused by a human papillomavirus.
intraductal papillary mucinous neoplasm (4 papers, 2015 to 2025). "Investigations into the presence of PIK3CA mutations in pancreatic lesions have included studies examining intraductal papillary mucinous neoplasms (IPMNs), intraductal tubulopapillary neoplasm and invasive cancers." (PMID 26436951, 2015). "However, somatic PIK3CA mutations have been commonly reported in the ITPNs of the pancreas, which is a rare subtype of premalignant pancreatic lesion, distinct from intraductal papillary mucinous neoplasm (IPMN)." (PMID 35008235, 2021). "Intraductal papillary mucinous neoplasm (IPMN) maintains the majority of alterations associated with PDA except SMAD4 losses and differentially presents mutations in PIK3CA, GNAS and RNF43." (PMID 33669845, 2021).
lipoma (4 papers, 2014 to 2021). A benign, usually painless, well-circumscribed lipomatous tumor composed of adipose tissue. "Both the lipoma and the ovarian cyst had a PIK3CA pathogenic variant, c.1624G>A p.(Glu542Lys), present at less than 5% in the lipoma and at 29%–38% in the ovarian cyst." (PMID 30761771, 2019).
medullary carcinoma (4 papers, 2015 to 2019). "Also, in their study, 82.9 % of no special type case and 88.2% of medullary carcinoma showed overexpression of PIK3CA." (PMID 34466540, 2019).
Merkel cell carcinoma (4 papers, 2012 to 2026). "The present study adds Merkel cell carcinoma to this list of human cancers harboring PIK3CA mutations, although in MCC these mutations occur obviously at a low frequency." (PMID 22363598, 2012). "Analysis of PIK3CA, AKT1 and pAKT T308 in Merkel cell carcinoma." (PMID 22363598, 2012).
mismatch repair deficiency (4 papers, 2014 to 2023).
mucinous ovarian cancer (4 papers, 2017 to 2024). An invasive malignant neoplasm that arises from the ovary and is characterized by the presence of malignant epithelial cells that contain intracytoplasmic mucin and may resemble the epithelial cells of the endocervix or gastrointestinal tract. "The genetic mutation analysis found three mutations which were KRAS 27 cases (54%), PIK3CA 4 cases (8%) and BRAF 1 case (2%) The ovarian mucinous carcinoma patients with KRAS mutation in our study showed excellent prognosis." (PMID 31030485, 2019). "The relationship between the PIK3CA and mucinous ovarian cancer has not been clearly studied." (PMID 31030485, 2019).
myocardial infarction (4 papers, 2018 to 2026). Gross necrosis of the myocardium, as a result of interruption of the blood supply to the area, as in coronary thrombosis. "Hence, we speculated that liquiritin was involved in cardioprotective effects by regulating abnormal autophagy mediated by PIK3CA in myocardial I/R injury models, which might offer a novel perspective in improving the treatment strategy targeting myocardial infarction." (PMID 41538663, 2026). "Considering all the sub-networks and the related pathways pinpointed by NASFinder, PI3-kinase subunit alpha (PIK3CA) and PI3-kinase regulatory subunit alpha (PIK3R1) were identified as the proteins shared among all pathways, with the exception of myogenesis and myocardial infarction." (PMID 29529088, 2018).
oral squamous cell carcinoma (4 papers, 2019 to 2025). "The mutation rate of PIK3CA appears to be greater in oral squamous cell carcinoma (OSCC) than in ESCC." (PMID 38616230, 2024). "Our study demonstrated that in oral squamous cell carcinoma PIK3CA protein is frequently expressed (59.34% patients)." (PMID 33287350, 2020).
oropharyngeal tumors (4 papers, 2014 to 2024). "Since our patient cohort consisted of a majority of male patients with oropharyngeal, HPV-positive cancers, this result suggests a trend towards a high frequency of PIK3CA mutations among HPV (+) oropharyngeal tumours." (PMID 35267596, 2022). "We found that PIK3CA mutations occurred in 28% of the HPV-positive oropharyngeal tumors versus 10% of the HPV-negative samples, confirming that this is an important therapeutic target in HNSCC." (PMID 25428177, 2014). "PIK3CA amplification (but not PIK3CA mutation) was associated with poorer progression-free survival (PFS), while RAS mutations were associated with poorer PFS and overall survival (OS) in a series enriched in patients with oropharyngeal tumors." (PMID 39613893, 2024).
ovarian carcinosarcoma (4 papers, 2015 to 2026). A highly aggressive malignant neoplasm arising from the ovary. "Molecular analysis using next-generation sequencing identified PIK3CA H1047R (c.3140A > G) and CSF1R (c.∗1841TG > GA) in both the epithelial and mesenchymal components, indicating a clonal origin and supporting a diagnosis of primary ovarian carcinosarcoma." (PMID 42211942, 2026).
penile cancer (4 papers, 2013 to 2024). A primary or metastatic malignant neoplasm that affects the penis. "A recent report showed a dysregulation of phosphatidylinositol 3-kinase and Ras pathways through somatic alterations of the PIK3CA, HRAS and KRAS genes in 11 out of 28 (39%) penile cancer samples, without any statistically significant difference between HPV-positive and HPV-negative cases." (PMID 23305393, 2013).
pulmonary fibrosis (4 papers, 2017 to 2026). Chronic progressive interstitial lung disorder characterized by the replacement of the lung tissue by connective tissue, leading to progressive dyspnea, respiratory failure, or right heart failure. "It is worth noting that the PIK3CA gene is a key component in the PI3K/Akt pathway, which plays a critical role in the development pulmonary fibrosis." (PMID 36217380, 2022). "protein–protein interaction protein interaction network analysis showed that PIK3CA, PIK3R1, MAPK1, SRC, AKT1, and so on may be the core targets of the compound Hongjingshen recipe in the treatment of pulmonary fibrosis." (PMID 36595795, 2022).
rheumatoid arthritis (4 papers, 2022 to 2025). A chronic, systemic autoimmune disorder characterized by inflammation in the synovial membranes and articular surfaces. "According to the results of molecular docking, in the context of rheumatoid arthritis, phytocannabinoids may bind to important target proteins such as PIK3CA, AKT1, MAPK9, PRKCD, BRAF, IGF1R, and NOS3." (PMID 36983855, 2023).
type 2 diabetes mellitus (4 papers, 2020 to 2025). A type of diabetes mellitus that is characterized by insulin resistance or desensitization and increased blood glucose levels. "For example, the pathway of the disease of type II diabetes mellitus, is correlated to tobacco smoking, and the genes involved are ADIPOQ, PIK3CA, and SLC2A2." (PMID 32455963, 2020).